SHARPIN (SHANK associated RH domain interactor)
Diseases named in the same sentence as SHARPIN in open-access papers (continued):
Sharing a sentence is not in itself a finding about the gene and the disease.
Hepatitis (1 paper, 2017). Inflammation of the liver. "In conclusion, to our knowledge, this is the first report showing that LUBAC formation, particularly the SHARPIN expression level, is reduced in the livers of mice with toxic agent-induced hepatitis." (PMID 28165393, 2017). "LUBAC formation, especially the SHARPIN expression level, was reduced in the livers of mice with CCl4- or APAP-induced hepatitis." (PMID 28165393, 2017). "In fact, it was clearly shown that hepatic knockdown of either SHARPIN or HOIP by adenoviral transfer of the corresponding shRNA into mice produced severe inflammation and fibrosis accompanied by hepatocyte death, features typically observed in both drug-induced hepatitis and NASH livers." (PMID 28165393, 2017).
inflammatory skin disease (1 paper, 2015). Inflammatory skin disorders covers a broad category that includes many conditions ranging in severity, from mild itching to grave medical health complications These disorders are common in people of all ages and races. "HOIL-1 KO mice were born at Mendelian ratios and, in contrast to SHARPIN-deficient mice, failed to develop TNFα-driven inflammatory skin disease and exhibited normal histology of lymphoid organs, liver, lung, and kidney, and the presence of Peyer's patches along the small intestine (not shown)." (PMID 25599590, 2015).
leukemia (1 paper, 2024). A malignant (clonal) hematologic disorder, involving hematopoietic stem cells and characterized by the presence of primitive or atypical myeloid or lymphoid cells in the bone marrow and the blood. "Furthermore, to investigate the effects of the HOIL-1L R464H variant in human immune cells, HOIL-1L WT or mutant HOIL-1L, along with HOIP and SHARPIN, were introduced into a human leukemia monocytic cell line, THP-1, using a retrovirus transduction system." (PMID 38329126, 2024).
lung adenocarcinoma (1 paper, 2017). A carcinoma that arises from the lung and is characterized by the presence of malignant glandular epithelial cells. "Interestingly, elevated SHARPIN expression was found in both human lung adenocarcinoma and squamous cell carcinoma compared with that in normal lung samples." (PMID 28903384, 2017). "Similar to the observations regarding alterations in SHARPIN expression in cancer, the expression level of PRMT5 was also found to be dramatically elevated in both human lung adenocarcinoma and squamous cell carcinoma compared with that in normal lung samples by analysis of RNA-sequencing from TCGA." (PMID 28903384, 2017).
lymphoma (1 paper, 2018). A malignant (clonal) proliferation of B- lymphocytes or T- lymphocytes which involves the lymph nodes, bone marrow and/or extranodal sites. "We then examined the therapeutic potential of inhibition of the HOIL-1L/SHARPIN interaction for treating ABC-DLBCL, using HBL1 cells derived from lymphoma patients." (PMID 29694895, 2018).
malaria (1 paper, 2021). Malaria is a serious and sometimes fatal disease caused by a parasite that commonly infects a certain type of mosquito which feeds on humans. "Conversely, the other five key genes (MBP, SPSB3, PSMF1, SHARPIN, and EIF3B) were negatively correlated with malaria severity and decreased in CM." (PMID 33942992, 2021). "Within the nine genes, five genes (MBP, SAMSN1, PSMF1, SLC39A8, and EIF3B) were previously found to be involved in malaria, and the remaining four genes (SMPDL3A, FABP5, SPSB3, and SHARPIN) were identified for the first time in the current study." (PMID 33942992, 2021). "SAMSN1, SLC39A8, SMPDL3A, and FABP5 were positively correlated with malaria phenotype/severity and showed an upregulation in the CM group compared with healthy controls, while MBP, SPSB3, PSMF1, SHARPIN, EIF3B were negatively correlated with malaria severity and downregulated in the DEG." (PMID 33942992, 2021).
mild cognitive impairment (1 paper, 2022). "Six highly deleterious variants of SHARPIN, comprising four missense variants, one frameshift variant, and one stop-gain variant were detected from whole-genome sequencing data for 180 patients with LOAD and 184 with mild cognitive impairment." (PMID 34737388, 2022).
nonalcoholic steatohepatitis (1 paper, 2025). "In a mouse model of nonalcoholic steatohepatitis (NASH), hepatic fatty acid accumulation likely disrupts LUBAC assembly by reducing SHARPIN expression, thereby impairing downstream NF-κB activation." (PMID 41446873, 2025).
renal cell carcinoma (1 paper, 2022). "Overexpression of SHARPIN leads to elevated intracellular HIF2α in patients with Renal cell carcinoma." (PMID 35547743, 2022). "Therefore, SHARPIN promotes the development of renal cell carcinoma via enhancing the degradation of the tumor suppressor pVHL." (PMID 35547743, 2022).
serous ovarian cancer (1 paper, 2021). "In the serous ovarian cancer patients of cohort 2 (n = 20/80), detectable antibodies (Z-scores > 0) were seen against CTAG2 (n = 3/20, 15%), SHARPIN (n = 2/20, 10%), PNMA2 (n = 2/20, 10%), MAGEB4 (n = 1/20, 5%), MRFAP1L1 (n = 1/20, 5%), SERPINB1 (n = 1/20, 5%) and XAGE3 (n = 1/20, 5%)." (PMID 34681879, 2021).
skin cancer (1 paper, 2023). "Whether SHARPIN-mediated linear ubiquitination is involved in skin cancer needs further investigation." (PMID 38017534, 2023).
synovial sarcoma (1 paper, 2023). "Moreover, transferrin receptor 1 (TFRC) and SHANK-associated RH domain interactor (SHARPIN), both of which are oncogenic factors and related to poor overall survival, are highly expressed, particularly in synovial sarcoma cell lines." (PMID 37444594, 2023). "To elucidate the role of SHARPIN, an activator of NF-κΒ, on ferroptosis, we performed a knockdown experiment in synovial sarcoma cell lines." (PMID 37444594, 2023). "In addition, analyses of clinical samples revealed that SHARPIN mRNA expression was significantly higher (p < 0.005) in synovial sarcoma (n = 40) than in normal tissue (n = 10)." (PMID 37444594, 2023). "Notably, the SHARPIN mRNA level in the four synovial sarcoma cell lines was more than twice as high as that in HDF." (PMID 37444594, 2023). "SHARPIN controls the activities of NF-κΒ and PRMT5, which regulate the production of ROS and are involved in both apoptotic and nonapoptotic cell death; hence, we analyzed whether knockdown of SHARPIN inhibits the activities of NF-κΒ and PRMT5 in synovial sarcoma (Yamato) cells." (PMID 37444594, 2023).
uterine leiomyosarcoma (1 paper, 2021). "An in vitro study showed the oncogenic function of the SHARPIN gene in uterine leiomyosarcoma." (PMID 34178683, 2021).
uterine sarcoma (1 paper, 2021). "Knockdown of SHARPIN expression was observed to decrease cell growth and colony formation in uterine sarcoma cell lines." (PMID 34178683, 2021). "Knockdown of SHARPIN expression decreased cell growth and cell colony formation in uterine sarcoma cell lines." (PMID 34178683, 2021). "Furthermore, our cell function study confirmed that SHARPIN plays an important role in uterine sarcoma cell proliferation and cell colony formation." (PMID 34178683, 2021).
Yersinia infection (1 paper, 2019). "This could occur when RIPK1 kinase-dependent cell death is beneficial for the host, such as following Yersinia infection, or in disease conditions caused by genetic mutations, such as the spontaneous mutation that arose in SHARPIN in the chronic proliferative dermatitis mice (Shpncpdm/cpdm)." (PMID 30988283, 2019). "Importantly, mimicking Ser25 phosphorylation compromises the in vivo cell death-dependent immune control of Yersinia infection, a physiological model of TAK1/IKK inhibition, and rescues the cell death-induced multi-organ inflammatory phenotype of the SHARPIN-deficient mice." (PMID 30988283, 2019).
cancer (18 papers, 2015 to 2025). A tumor composed of atypical neoplastic, often pleomorphic cells that invade other tissues. "Analysis of a TCGA dataset including all types of cancer suggested that amplification of either the SHARPIN gene or the TFRC gene is associated with DFS." (PMID 37444594, 2023). "SHARPIN plays tumor-associated roles during cancer biogenesis by promoting cell survival, growth, and invasion." (PMID 28903384, 2017). "Additionally, the integrin inhibitor shank-associated RH domain-interacting protein (SHARPIN) has been found to regulate integrin activity and migration in cancer cells and white blood cells in vitro." (PMID 39940673, 2025). "SHARPIN has been implicated in the pathologic progression in several cancers." (PMID 28903384, 2017). "The identification of a small molecule that inhibits the ubiquitin-binding activity of both HOIL-1L NZF and SHARPIN NZF provides a potential therapeutic strategy for targeting elevated LUBAC activity in diseases such as cancer." (PMID 39528476, 2024). "Next, we analyzed the relationship between SHARPIN expression and patient survival using existing data for 10,967 samples in the TCGA database, including all types of cancer." (PMID 37444594, 2023). "By contrast, in another cohort of samples (ICGC/TCGA Pan-Cancer Analysis of Whole Genomes Consortium, 2020; n = 362), including all types of cancer, SHARPIN gene amplification and/or high mRNA expression was associated with shorter OS." (PMID 37444594, 2023). "Given that cell mobility and invasiveness are key features of the malignant cancer cells, the effect of SHARPIN on cell mobility was investigated by a wound-healing assay." (PMID 35547743, 2022). "The amplified region contains co-localized PAN cancer gene signatures of UTP23 and SHARPIN gene signatures, and it has enabled the clustering of 21 human cancer types into seven cross-cancer gene signatures based on coregulated genes." (PMID 36497066, 2022). "Integrin-binding partner proteins, such as kindlins and SHARPIN, are also expressed in cancer and immune cell exosomes (unpublished data)." (PMID 33672100, 2021). "They found that cisplatin-resistant cancer cell lines show a significantly higher expression of HOIP and SHARPIN when compared with cisplatin-sensitive cancer cell lines." (PMID 34769306, 2021). "On the other hand, the expression levels of signature UTP23 and signature SHARPIN are independent although these two signatures are co-amplified in 77.6% of the cancer cases." (PMID 33057153, 2020). "SHARPIN expression is frequently high in multiple human cancer types, including liver, ovarian, prostate, and breast cancer." (PMID 28903384, 2017). "In a detailed model, our findings suggest that SHARPIN is responsible for mediating the expression of cancer metastasis-related genes, which leads to changes in the mobility of cancer cells." (PMID 28903384, 2017). "SHARPIN is mainly localized in the cytoplasm of cancer cells; however, a fraction of SHARPIN is also localized in the nucleus, which implies that SHARPIN can interact with specific transcription factors to regulate gene expression." (PMID 28903384, 2017). "SHARPIN can promote K48-linked ubiquitination and degradation, and it can associate with YAP and promotes YAP degradation which in turn leads to reduced YAP transcriptional activity and the ability of cancer cells to progress." (PMID 35547743, 2022). "SHARPIN promotes cancer cell survival, growth, invasion and metastasis." (PMID 34178683, 2021). "Furthermore, SHARPIN suppresses the endogenous activity of β1 integrins in cancer cells and primary leukocytes." (PMID 33672100, 2021). "SHANK-associated RH domain interacting protein (SHARPIN) is a ubiquitin-related protein involved in several processes, including inflammatory responses, the development of both normal and cancer tissues, and inhibition of integrin activity in different cell types." (PMID 32604738, 2020).
cancer (continued). "Moreover, we found PRMT5 as a novel cofactor of SHARPIN in regulating cancer-related gene expression." (PMID 28903384, 2017). "SHARPIN is involved in regulating inflammation and cancer progression." (PMID 28903384, 2017). "Some of the SHARPIN mutants described in this study could be utilized to determine how the distinct SHARPIN functions contribute to cancer progression." (PMID 26600301, 2015). "SHARPIN has proto-oncogenic effects and may be involved in cancer development and progression." (PMID 35547743, 2022). "Thus, we further questioned whether PRMT5 as a novel cofactor of SHARPIN also plays an important role in the invasion of cancer cells." (PMID 28903384, 2017). "Importantly, SHARPIN is amplified in a wide variety of human cancer types (BioPortal.org;)." (PMID 26600301, 2015). "Studies have also shown that SHARPIN can interact with PRMT5, which can facilitate the transcription of regulatory cancer-related genes." (PMID 35547743, 2022). "Since PRMT5 is also widely involved in the pathologic progress of cancer metastasis, we tested if PRMT5 was a target of SHARPIN." (PMID 28903384, 2017). "The ChIP-qPCR profile of all these histone PTMs supports the idea that SHARPIN is essential for PRMT5 in maintaining unique H3 arginine methylation (H3R2me1), which surrounds the promoter regions of cancer metastasis-related genes." (PMID 28903384, 2017). "In this study, we found that SHARPIN activates PRMT5 to specifically target histone H3R2 for monomethylation, which is responsible for the subsequent activation of cancer-related genes." (PMID 28903384, 2017). "The phosphorylation on SHARPIN at serine 146 selectively mediates SHARPIN’s interaction with the ARP2/3 complex, a protein interaction that may provide a target for therapeutic interference in cancer." (PMID 35547743, 2022).
tumor (18 papers, 2013 to 2025). "To test the effects of SHARPIN deficiency on tumor growth, we injected equal numbers of WT or SHARPIN-deficient B16F1 cells s.c. into opposing flanks of WT B6 hosts." (PMID 34752416, 2021). "Increased integrin activity due to loss of SHARPIN protein would affect the uptake of the αvβ3-selective 23, both in several tissue types and in the tumor microenvironment." (PMID 33810198, 2021). "Consistent with previous reports, the anti-PD1 partially reduced WT tumor size/growth but remarkably, and within the same animals, eliminated the SHARPIN-deficient tumors, demonstrating synergism." (PMID 34752416, 2021). "Aberrant SHARPIN expression promotes growth mediated by xenografted tumor cells in immunodeficient mice." (PMID 35547743, 2022). "These correlations decreased for tumor tissues, as SHARPIN mRNA expression level was moderately correlated with RBCK1 and RNF31 mRNA expression levels (r = 0.52 and r = 0.48, respectively)." (PMID 29763465, 2018). "In this study we extend these findings by demonstrating that the mRNA levels of RBCK1 and SHARPIN are also higher in tumors compared to adjacent non-tumor tissue in the same cross sectional study of samples (p < 0.001)." (PMID 29763465, 2018). "SHARPIN has been previously shown to have significant elevation of expression in BC in comparison to non-tumor breast tissues, but to our knowledge we are the first to show that SHARPIN is a BC metastasis gene." (PMID 26506596, 2015). "In previous studies, it had been reported that the expression of HOIL-1 and SHARPIN was upregulated in tumor tissues and exerted oncogenic functions by stabilizing the expression HOIP and promoting the transactivation of Versican expression; however, it was independent of their M1-Ubi activity." (PMID 41053347, 2025). "In addition, the protein levels of the other two components of LUBAC, HOIP and SHARPIN were upregulated in the tumor tissues, as evidenced by western blot." (PMID 41053347, 2025). "ROC Curve analysis revealed that up-regulated RNF31, RBCK1 and SHARPIN mRNA expression had high predictive abilities to distinguish tumor tissues from adjacent non-tumor tissues, with the Area Under the Curves (AUCs) being equal to 0.95, 0.94 and 0.91, respectively." (PMID 29763465, 2018). "SHARPIN, a multifunctional molecule, participates in a variety of biological processes, including activation of nuclear factor-κB signaling and inhibition of tumor suppressor genes." (PMID 28903384, 2017). "Another report indicated knockdown of SHARPIN could inhibit ccRCC tumor growth in xenograft models." (PMID 37908350, 2023). "Together with the observed differential growth in the WT animals, these results showed that an increased susceptibility to RIPK1-dependent cell death (conferred by SHARPIN deficiency) does not result in spontaneous tumor cell death, but rather sensitizes to T cell–mediated tumor destruction." (PMID 34752416, 2021). "Knockdown of SHARPIN in TE354.T cells, a human BCC cell line, enhanced tumor cell proliferation, possibly due to the increased phosphorylation of two transcriptional factors, c‐JUN and GLI family zinc finger 2 (GLI2)." (PMID 38017534, 2023). "First, SHARPIN mutant mice exhibiting chronic proliferative dermatitis suggest that SHARPIN is not only an indolent scaffold protein but may also activate cell migration and proliferation, and therefore may be involved in the aberrant proliferation of tumor cells." (PMID 35547743, 2022). "Taken together, it is suggested that SHARPIN is a PTEN-NR and that it promotes the tumor by inhibiting the function of PTEN, and at least in part promotes tumorigenesis." (PMID 35547743, 2022). "Thus, there was a close relationship between the tumor immune microenvironment and this prognostic signature based on TAK1, CDK1, and SHARPIN." (PMID 37313428, 2023).
tumor (continued). "Regarding to SHARPIN (SHANK Associated RH Domain Interactor), we found that although its expression alteration was not remarkable in primary tumor tissues, it was significantly upregulated in metastatic ccRCC." (PMID 37908350, 2023). "Our previous studies showed that SHARPIN and RNF187 could promote YAP degradation and inhibit tumor progression." (PMID 36581998, 2022). "In this study we extend this observation by determining mRNA and protein expression levels of the two additional components of the LUBAC complex, RBCK1 and SHARPIN as well as RNF31 protein expression in the same cross sectional study of cancer tumors and adjacent non-tumor tissues." (PMID 29763465, 2018). "SHARPIN expression was significantly elevated in ERBB2 negative compared to ERBB2 positive tumor samples (p < 0.05)." (PMID 26506596, 2015). "Since clinicopathological data for tumor samples including ERalpha, PR and HER2 protein expression and also clinical staging, histological grading, lymph node and menopausal statuses were available, we further examined the mRNA expression of RBCK1, RNF31 and SHARPIN in relation to these data." (PMID 29763465, 2018).